IL6 (interleukin 6)
Diseases named in the same sentence as IL6 in open-access papers (continued):
Sharing a sentence is not in itself a finding about the gene and the disease.
oropharyngeal tumors (1 paper, 2019). "IL-6 induction suggests E6* as a pro-inflammatory oncogene, while other works have pointed out the alternate E6*I protein as the most abundant oncogene transcript in premalignant or malignant cervical and oropharyngeal tumors." (PMID 31396215, 2019).
Osteoblastoma (1 paper, 2011). A rare benign bone-forming neoplasm usually arising from the spine. "Different regulation of Il6 in human osteoblastoma and rodent glial or neuronal cells can be a result of tissue- and species-specificity of estrogen effects." (PMID 21774811, 2011). "However, Il6 shows down-regulation by E2 in osteoblastoma Saos-2 cells, in contrast to the up-regulation we report in the frontal cortex." (PMID 21774811, 2011).
osteophytes (1 paper, 2010). "This may explain why previous reports suggested that both leptin and IL-6 are highly expressed in osteophytes, yet we were unable to describe any associations between osteophytes and serum levels of either." (PMID 20482813, 2010). "We found that serum leptin levels in both sexes and serum IL-6 levels in women were positively associated with hip JSN, but not with osteophytes." (PMID 20482813, 2010). "We found no significant relations between leptin, IL-6, and the presence or severity of osteophytes (data not shown)." (PMID 20482813, 2010).
otitis media with effusion (1 paper, 2025). Otitis media associated with accumulation of fluid in the middle ear. "A comparative histological study of 9 children with otitis media with effusion and 11 patients with chronic otitis media and tympanosclerosis showed a higher expression of macrophages, B cells, and IL-6 in the otitis media with effusion group." (PMID 40227356, 2025). "The levels of IL-2, IL-6, IgE, and NO in MEE were significantly higher than those in peripheral blood in the experimental group (p < 0.01), suggesting that the increase in NO levels is involved in the pathogenesis of otitis media with effusion." (PMID 40227356, 2025).
ovarian disorder (1 paper, 2025). A disease involving the ovary. "In conclusion, the results showed that IL-6, miRNAs, and autophagy processes work together to control inflammation and cellular repair in ovarian disorders." (PMID 41227338, 2025).
ovarian hyperstimulation syndrome (1 paper, 2024). A complication of ovulation induction in infertility treatment. "On the other hand, buffaloes that did not respond to treatment suffered from several pathological conditions of the ovary and uterus, as noted in our histopathological examination.IL-1, IL-6, IL-8, and TNF-α levels were found to be increased in ovarian hyperstimulation syndrome." (PMID 39495423, 2024).
ovarian serous cystadenocarcinoma (1 paper, 2019). A malignant serous cystic epithelial neoplasm arising from the ovary. "So the ascites Cyr61 and IL-6 levels of ovarian serous cystadenocarcinoma were detected, respectively." (PMID 31766991, 2019). "We further examined the expression patterns of Cyr61, IL-6, CRP and neutrophil percentage in peripheral blood of patient with early or advanced stage of ovarian serous cystadenocarcinoma." (PMID 31766991, 2019).
parathyroid disease (1 paper, 2023). "On the contrary, a study concluded that the mean serum concentrations of IL-6, CRP, and ESR had increased one year after surgical cure of the parathyroid disease (p < 0.001, p < 0.01, and p < 0.001, respectively)." (PMID 37858254, 2023).
parkinsonian tremor (1 paper, 2019). "However, to our knowledge, no studies have examined the role of IL-6 on parkinsonian tremor." (PMID 30971879, 2019).
partial seizures (1 paper, 2019). "IL-6 levels are strongly increased after recurrent GTCS, whereas after single tonic-clonic or prolonged partial seizures IL-6 levels are increased to a lesser extent." (PMID 31312171, 2019).
Patent ductus arteriosus (1 paper, 2020). In utero, the ductus arteriosus (DA) serves to divert ventricular output away from the lungs and toward the placenta by connecting the main pulmonary artery to the descending aorta. "Elevated CRP and/or IL-6 in clinical routine samples from cord blood were found in the high S100A group only, while the only significant difference regarding neonatal morbidities was a higher percentage in need of treatment for patent ductus arteriosus in the high S100A group." (PMID 32612607, 2020).
Pca (1 paper, 2018). "in vitro, some studies have found that both interleukin-6 (IL-6) and epidermal growth factor (EGF) can activate Akt and its pathway to promote Pca progression." (PMID 29416748, 2018).
peanut allergy (1 paper, 2021). "On an epigenomic level, hypomethylation of IL-6 has been shown in children with peanut allergy, and it has also been associated to worse lung function in asthmatic children." (PMID 34193262, 2021).
pediatric acute respiratory distress syndrome (1 paper, 2022). "Annotation: PARDS: pediatric acute respiratory distress syndrome; TNF-α, tumor necrosis factor -alpha; IL-6, interleukin-6; IL-1β; IL-17: interleukin-17." (PMID 35506305, 2022).
pediatric cancers (1 paper, 2025). "In pediatric cancers, higher levels of IL-6 were detected in patients with poorer prognosis, since IL-6 is known to contribute to accelerated tumor growth." (PMID 39796780, 2025). "IL-6 is known to play a role in various physiological processes such as immune function, inflammation, development, and bone metabolism, all of which are affected in pediatric cancer development and metastasis." (PMID 39796780, 2025).
pelvic organ prolapse (1 paper, 2024). Abnormal descent of a pelvic organ resulting in the protrusion of the organ beyond its normal anatomical confines. "Our findings revealed a significant elevation in interleukin (IL)‐6 and TNF‐α, and matrix metalloproteinase‐2 (MMP2) levels in the vaginal wall tissues of patients with pelvic organ prolapse (POP) compared with the control group." (PMID 38898783, 2024). "To compare the levels of IL‐6, TNF‐α and MMP2 in vaginal wall tissues between patients diagnosed with pelvic organ prolapse and a control group, we gathered a total of 80 vaginal wall tissue samples." (PMID 38898783, 2024).
penile squamous cell carcinoma (1 paper, 2025). "Immunohistochemistry (IHC) analysis of eight cytokines (IL-1A, IL-1B, IL-2, IL-6, IL-12, TGF-β1, TNF-α and IFN-γ) was performed in paired tumour tissues and corresponding negative surgical margins from 94 patients with penile squamous cell carcinoma." (PMID 41465261, 2025).
penile tumour (1 paper, 2025). "Transcriptomic analyses have demonstrated the elevated mRNA expression of IL-1A, IL-1B, IL-6, IFN-γ, and TGF-β1 in penile tumour tissue, with a positive correlation between IFN-γ levels and tumour stage." (PMID 41465261, 2025).
periapical tissue disease (1 paper, 2025). Any disease of the periapical tissue. "IL-6 positively correlated with decayed permanent teeth and pulp/periapical tissue diseases, whereas IL-18 correlated with white spot lesions and pulp infections." (PMID 40243946, 2025).
Pf (1 paper, 2019). "The IL-6 levels, in comparison with NT groups, were found to be decreased in ST patients during Pv and Pf infections." (PMID 31110658, 2019).
pharyngeal squamous cell carcinoma (1 paper, 2024). A squamous cell carcinoma that arises from the pharynx. "On the other hand, the expression levels of Th2 CKs IL-6 and IL-8 were higher in pharyngeal squamous cell carcinoma than in benign lesions, consistent with previous literature." (PMID 38920620, 2024).
photokeratitis (1 paper, 2008). Injury to the cornea secondary to ultraviolet light. "Nevertheless, it is also possible that the low level of IL-6 may act as a trigger to exert the inflammatory response of the stromal cells, the primary cause of photokeratitis." (PMID 18769647, 2008).
photosensitivity dermatitis (1 paper, 2025). "Inflammatory mediators, including tumor necrosis factor‐alpha (TNF‐α), Interleukin 6 (IL‐6), and interferon‐gamma (IFN‐γ), further promote keratinocyte apoptosis and immune cell recruitment, exacerbating photodamage and increasing the likelihood of photosensitivity dermatitis." (PMID 41458916, 2025).
pleural mesothelioma (1 paper, 2021). A neoplasm that arises from the mesothelial cells of the pleura. "We collected the methylation profile of pleural mesothelioma, and found 8 novel interactors to be hypomethylated in pleural mesothelioma versus non-tumor pleural tissue, namely, ACVR1B, IL6, MGMT, NRG1, OAT, PHLDA2, PLAUR and TNC." (PMID 33916178, 2021).
Pneumocystis infection (1 paper, 2024). "In addition, studies of human COPD patients infected with Pneumocystis jirovecii (the causative agent of human Pneumocystis infection) showed that the detection of this fungus correlates with higher pro-inflammatory cytokines levels, such as TNFα, IL6, and IL8." (PMID 38542124, 2024).
Polyhydramnios (1 paper, 2021). The presence of excess amniotic fluid in the uterus during pregnancy. "Although subtle changes in IL-6 secretion were observed upon hAFSC neurogenic induction (in hAFSCs from healthy gestations, secretion was downregulated, while in hAFSCs from polyhydramnios, it was slightly upregulated), observed differences were not statistically significant." (PMID 34336852, 2021).
post-thrombotic syndrome (1 paper, 2025). A condition characterized by a chronically swollen limb, often a leg with stasis dermatitis and ulcerations. "Several studies have also shown an association between plasma levels of IL-6, VTED, and post-thrombotic syndrome." (PMID 40940731, 2025).
pregnancy toxemia (1 paper, 2025). "Pregnancy toxemia (PT) does exhibit significantly elevated expression of IL-6 and IL-8 compared with healthy controls, with fold changes of 3.8 (95% CI: 2.9–4.7) and 3.1 (95% CI: 2.4–3.9), respectively." (PMID 41012815, 2025). "PCR-DNA sequence analysis revealed that the amplified fragments of IL-6 (627 bp), IL-8 (264 bp), FASN (381 bp), SOD3 (393 bp), HMOX1 (460 bp), and ACACA (477 bp) differed between healthy goats and those affected by pregnancy toxemia (PT)." (PMID 41012815, 2025).
pregnancy-induced hypertension (1 paper, 2023). "Levels of inflammatory mediators (IL-6, TNF-α, and hs-CRP) in pregnancy-induced hypertension (PIH) patients have a positive link with the SBP and a poor fetal prognosis of patients, which could be utilized as a parameter of prognosis estimation of PIH patients." (PMID 37759223, 2023).
Primary glaucoma (1 paper, 2020). "And in regard to the lack of IL-6 increase in primary glaucoma, it is interesting to note previous reports showing that soluble IL-6 receptor (sIL-6R) but not IL-6 is elevated in the aqueous humour of POAG49." (PMID 33060644, 2020).
primary hyperparathyroidism (1 paper, 2014). "In primary hyperparathyroidism, the parathyroid glands contribute markedly to IL-6 production and elevate the serum IL-6 level." (PMID 24558316, 2014).
proliferative inflammatory atrophy (1 paper, 2022). A lesion in the prostate gland characterized by glandular atrophy, chronic inflammation, and epithelial hyperplasia. "Indeed, microbial toll-like receptor downstream inflammatory cytokines (e.g., IL-6) contribute to proliferative inflammatory atrophy (PIA), which is a precursor of prostatic intraepithelial neoplasia (PIN) and PCa." (PMID 35155686, 2022).
Pseudomonas infection (1 paper, 2016). Infections with bacteria of the genus pseudomonas. "The levels of plasma IL-6, TNF-α, IFN-γ and MIP-2 were significantly higher in infected mice and in the IL-15 SA-treated mice receiving intraperitoneal Pseudomonas infection as compared to vehicle treated infected mice." (PMID 26859674, 2016).
ptosis (1 paper, 2011). The drooping of the upper eyelid. "For instance, IL-1b, IL-6 and TNF-α have well documented sickness effects (e.g. ptosis, piloerection, curled body posture) that are related to hypothalamic neurochemical activity." (PMID 21745392, 2011).
pulmonary regurgitation (1 paper, 2026). "The Sch-PH group had significantly lower tricuspid annular plane systolic excursion and pulmonary artery acceleration time/pulmonary ejection time ratio (P<0.05), and increased pulmonary artery peak flow, tricuspid and pulmonary regurgitation, IL-6, and TGF-β1 levels (P<0.05)." (PMID 41637287, 2026).
radiation-induced brain injury (1 paper, 2017). An injury to the brain which results results from exposure to radiation. "Patients with radiation-induced brain injury show high levels of extracellular ATP, IL-6, and TNF in cephalorachidian fluid." (PMID 28962574, 2017).
RASopathy (1 paper, 2017). Developmental syndromes caused by germline mutations (or in rare cases by somatic mosaicism) in genes that alter the Ras subfamily and mitogen-activated protein kinases that control signal transduction. "Furthermore, anti-TNF and/or IL6 signalling pathway agents might prove beneficial as targeted therapy for treating RASopathy patients with severe LVH." (PMID 28548091, 2017).
reactive depression (1 paper, 2021). "We were still able to observe different patterns by IL-6 status; and in condition with lower IL-6 level, men with reactive depression showed decreased MMSE." (PMID 34184172, 2021).
Renal amyloidosis (1 paper, 2021). A form of amyloidosis that affects the kidney. "Besides directly IL-6 targeting agents, Janus kinase inhibitors reduce IL-6 signaling, and they may have impressive SAA-reducing effects in RA but none of the available drugs (tofacitinib, baricitinib, upadacitinib, and filgotinib) have consistently been evaluated in renal amyloidosis." (PMID 33981717, 2021).
reovirus infection (1 paper, 2021). "However, overexpression of PARP9 in PARP9 and MAVS DKO BMDC did not affect the IL-6 production in response to intracellular poly I:C or viral dsRNA Reo1198 or reovirus infection." (PMID 33976210, 2021). "Additionally, MAVS KO or both PARP9 and MAVS DKO abrogated IL-6 production in response to intracellular poly I:C or reovirus infection, while PARP9 KO did not affect IL-6 production compared to WT BMDC." (PMID 33976210, 2021).
retina inflammation (1 paper, 2022). "LPS has been shown to enhance the hypoxic response created in DR by increasing the IL-6 and IL-8 expression in human retinal pigment epithelium cells, thus indicating that the increased presence of this unique bacterial capsule within the eye could contribute to retina inflammation." (PMID 34985498, 2022).
retroperitoneal fibrosis (1 paper, 2020). "IL-6 and IL-6R expression in the tissue lesions of IgG4-related retroperitoneal fibrosis and IgG4-related sialadenitis patients were also significantly higher than that in the normal tissues." (PMID 32733444, 2020).
rhinosinusitis (1 paper, 2025). "Elevated IL-6 and TNF-α are closely linked to rhinosinusitis severity and outcomes." (PMID 39870748, 2025).
rhinosporidiosis (1 paper, 2023). Chronic, localized granulomatous infection of mucocutaneous tissues, especially the nose, and characterized by hyperplasia and the development of polyps. "Since a cell-mediated immune response has been commonly implicated in rhinosporidiosis, in our study we have compared changes in cytokines of cell-mediated immunity- IL-6, IFN-γ, TNF-β- in patients with rhinosporidiosis and in controls without the disease." (PMID 38090617, 2023). "In our study we found a significantly increased levels of IL-6 and TNF-β (cytokines mostly associated with cell-mediated immunity) in patients with rhinosporidiosis but definite association with disease duration and recurrence was not elicited." (PMID 38090617, 2023). "The findings suggest that there is a role of cell-mediated immunity in rhinosporidiosis which needs to be explored further and cytokines like IL-6 and TNF-β may be part of the immune response." (PMID 38090617, 2023).
salivary gland disease (1 paper, 2020). "Another study found that in a co-culture of NOD mice salivary gland acinar cells (SGAC) and B-lymphocyte (an in-vitro model of salivary gland disease in SS), there was a significant increase in production of cytokines IL-6 and IL-1β by B-lymphocytes and increased phosphorylation of STAT3 in SGAC." (PMID 32849505, 2020).
salivary gland mucoepidermoid carcinoma (1 paper, 2015). A carcinoma that arises from the salivary glands. "Collectively, these data unveiled IL-6 as a therapeutic target for salivary gland mucoepidermoid carcinomas." (PMID 26287605, 2015).
salivary gland tumors (1 paper, 2025). "In patients with salivary gland tumors (WT and PA), various chemokines have been determined, including CCL28, CXCL10, CXCL12, CCL18, and CXCL1, as well as pro-inflammatory cytokines such as IL-1β, IL-6, IL-4, IL-17, and IL-33." (PMID 40807046, 2025).
Schnitzler syndrome (1 paper, 2022). A rare, underdiagnosed disorder in adults characterized by recurrent febrile rash, bone and/or joint pain, enlarged lymph nodes, fatigue, a monoclonal IgM component, leukocytosis and systemic inflammatory response. "Although anti IL-1 therapy is considered the therapy of choice for Schnitzler syndrome, there is emerging evidence that a subset of patients may respond to IL-6 antagonists instead." (PMID 35756635, 2022).
serous carcinoma (1 paper, 2025). "Furthermore, IL6 is strongly associated with disease stage and histological subtypes, particularly in high-grade serous carcinoma, where elevated levels correlate with more aggressive disease and poor prognosis." (PMID 40427188, 2025).
simian immunodeficiency virus infection (1 paper, 2011). An infection affecting monkeys, chimpanzees, and other non human primates caused by a HIV-like virus. "In simian immunodeficiency virus infection, innate immunity, IL-6, and interferon responses are important elements in brain viral control, but in a recent study expression of interferon-α in the brain was conclusively linked to neuronal dysfunction in a mouse model of HIVE." (PMID 21909266, 2011).
Sinus bradycardia (1 paper, 2022). Bradycardia related to a mean resting sinus rate of less than 50 beats per minute. "There are 54 targets of action in the treatment of sinus bradycardia, of which 19 targets such as AKT1, IL6, TNF, and VEGFA are the core targets of Datura metel in the treatment of sinus bradycardia." (PMID 36626429, 2022). "The results of the network screening of core targets showed that AKT1, IL6, VEGFA, and TNF were the top 4 core target proteins in terms of degree value, and maybe the most core targets for the treatment of sinus bradycardia with Yohimbe." (PMID 36626429, 2022).
skin thickening (1 paper, 2024). "A previous study also revealed that the level of serum IL-6 was closely related to skin thickening, which confirmed the important role of IL-6 in the development of SSc skin sclerosis." (PMID 39080112, 2024).
small intestinal tumors (1 paper, 2025). "Liu et al16 found the quantity of inflammatory mediators (IL-6, IL-1β, and TNF-α) in the small intestinal tumors of Apcmin/+ mice was higher than that in the control group." (PMID 40241344, 2025).
soft tissue tumors (1 paper, 2022). "Therefore, determining serum IL-6 levels may be used as a diagnostic tool to differentiate between benign soft tissue tumors and STS." (PMID 35267581, 2022).
spinal cord diseases (1 paper, 2024). "Previous studies have shown that serum GFAP is elevated in patients with brain or spinal cord diseases compared with healthy controls and is positively correlated with IL-6, a marker of inflammation, in patients with hepatic encephalopathy." (PMID 39459426, 2024).
spleen diseases (1 paper, 2024). "They speculated that the level of IL-6 might be related to the patient’s acute inflammatory response level or to concurrent bile duct, liver, and spleen diseases, and might be related to the patient’s prognosis." (PMID 38669380, 2024).
squamous cell tumors (1 paper, 2010). "It has been demonstrated that the increase of IL-8 and IL-6 and the increase of proteins such as C-reactive protein play an important role in the pathogenesis of H&N squamous cell tumors." (PMID 20184737, 2010).